PDLIM7 (PDZ and LIM domain 7)
Diseases named in the same sentence as PDLIM7 in open-access papers:
PDLIM7 is named in the same sentence as 176 diseases in open-access papers, as found by Europe PMC text mining. Sharing a sentence is not in itself a finding about the gene and the disease. The quoted sentences say what the papers report.
breast carcinoma (21 papers, 2003 to 2025). "Kaplan-Meier survival analysis revealed that the expression level of Pdlim7 is associated with poor survival of breast cancer patients." (PMID 30692208, 2019). "In this study, we identified Pdlim7 and Afadin as new interacting partners of Claudin-2 that contribute to the ability of breast cancer cells to grow in soft agar and form liver metastases." (PMID 30692208, 2019). "Together, these data demonstrate that Pdlim7 and Afadin are functionally involved in promoting the in vitro growth of breast cancer cells in soft agar and the formation of liver metastases in vivo." (PMID 30692208, 2019). "Several PDZ domain-containing proteins were identified that interact with the PDZ-binding motif of Claudin-2 in liver metastatic breast cancer cells, including Afadin, Arhgap21, Pdlim2, Pdlim7, Rims2, Scrib, and ZO-1." (PMID 30692208, 2019). "Although potential interacting proteins that bind this motif remain poorly defined, recent studies have identified Pdlim7 and Afadin as Claudin-2 interacting partner, which contribute to the ability of breast cancer cells to grow in soft agar and metastasize to the lungs and/or liver." (PMID 34079064, 2021). "Moreover, after comparing gene expression of breast cancer brain metastasis to bone metastasis, Pdlim7 appeared to be specifically expressed in bone metastasis." (PMID 30692208, 2019).
autoimmune disease (5 papers, 2012 to 2023). A disorder resulting from loss of function or tissue destruction of an organ or multiple organs, arising from humoral or cellular immune responses of the individual to their own tissue constituents. "Taken together, the PDLIM7/PDLIM2/p62-mediated degradation pathway to terminate p65 activation may prevent the onset of these autoimmune diseases and could be a novel molecular target for the treatment of autoimmune diseases." (PMID 32849529, 2020).
prostate carcinoma (5 papers, 2022 to 2025). A carcinoma that arises from epithelial cells of the prostate gland. "Subsequently, Ki67 immunohistochemical staining further confirmed that PDLIM7 overexpression significantly promoted the proliferative ability of prostate cancer cells." (PMID 36823643, 2023).
ovarian carcinoma (4 papers, 2016 to 2022). A malignant neoplasm originating from the surface ovarian epithelium. "In ovarian cancer, elevated expression of the ‘oncogenic gene set’ comprising IGF2BP1, SRF, FOXK1 and PDLIM7 was not significantly (P = 0.077) associated with poor overall survival (OS) but showed the expected trend with a HR of 1.22." (PMID 30371874, 2019).
thyroid cancer (4 papers, 2020 to 2025). "Enigma protein, encoded by the PDLIM7 gene, is overexpressed in thyroid cancer in a stage-dependent manner, suggesting a potential involvement in the initiation and progression of thyroid cancer." (PMID 38132395, 2023). "The observation of variable expression levels of the PDLIM7 gene in thyroid cancer tissues suggests heterogeneity within the cancer samples." (PMID 38132395, 2023). "The study suggests the potential utility of the PDLIM7-qPCR assay as a biomarker for thyroid cancer." (PMID 38132395, 2023). "Our research has provided additional valuable insights into the potential correlation between PDLIM7 and let-7g genes in thyroid cancer, as well as a detailed exploration of the Enigma and its associated pathways." (PMID 38132395, 2023). "Understanding this variability is crucial for deciphering the role of PDLIM7 in thyroid cancer progression." (PMID 38132395, 2023). "However, the statistical significance indicates a potential relationship between the dysregulation of let-7g and the expression of PDLIM7 in thyroid cancer." (PMID 38132395, 2023). "Understanding PDLIM7 gene expression levels could provide insights into the differentiation between early and advanced stages of thyroid cancer." (PMID 38132395, 2023). "Exploration of molecular and cellular mechanisms may discover the additional interaction between let-7g and PDLIM7 in thyroid cancer." (PMID 38132395, 2023). "We also see a significant but not a strong correlation between PDLIM7 and miR-let-7g gene in thyroid cancer tissues." (PMID 38132395, 2023). "miR-323-3p targets one of the PDLIM family genes, out of which we have observed that PDLIM7 (Enigma) is upregulated in the same thyroid cancer tissues but not in benign tumors via the activation of MAPK and c-MYC (unpublished data)." (PMID 34590612, 2021).
atherosclerosis (3 papers, 2017 to 2020). A disease characterized by the build-up of fatty material and calcium deposition in the arterial wall resulting in partial or complete occlusion of the arterial lumen. "Expression of two genes, ARID5B and PDLIM7 (PDZ and LIM domain protein 7), were positively associated with both measures of atherosclerosis (FDR ≤ 0.05); ARID5B was most significantly associated with carotid plaque score (P = 6.30 × 10−8, FDR = 1.08 × 10−3; with CAC: P = 2.47 × 10−5, FDR = 0.03)." (PMID 28855511, 2017). "Expression levels of two genes were associated with atherosclerosis at both sites: ARID5B (AT-rich interactive domain-containing protein 5B), a transcriptional co-activator involved in metabolic activities such as adipogenesis and PDLIM7 (PDZ and LIM domain protein 7) which promotes mineralization." (PMID 32582174, 2020). "In addition, its expression is positively correlated to typical smooth muscle cell markers in atherosclerosis plaques, and PDLIM7 silencing in vitro led to downregulation of smooth muscle cell (SMC) markers, disruption of actin cytoskeleton, decreased cell spreading, and increased proliferation." (PMID 32802835, 2020).
acute myeloid leukemia (2 papers, 2022 to 2023). Acute myeloid leukemia (AML) is a group of neoplasms arising from precursor cells committed to the myeloid cell-line differentiation. "In acute myeloid leukemia (AML), high expression of PDLIM7 is an independent risk factor for poor event-free survival (EFS) and overall survival." (PMID 37894409, 2023).
Hepatic fibrosis (2 papers, 2013 to 2021). The presence of excessive fibrous connective tissue in the liver. "PDLIM7 is composed of PDZ and LIM7 domain, the LIM7 domain is associated with progression of liver fibrosis in hepatitis C virus infected patients." (PMID 33971821, 2021).
non-small cell lung carcinoma (2 papers, 2015 to 2018). A group of at least three distinct histological types of lung cancer, including non-small cell squamous cell carcinoma, adenocarcinoma, and large cell carcinoma. "Although PDLIM7 is ubiquitously expressed in the liposarcoma and non-small cell lung cancer cell lines we examined here, its association with MDM2 was cell type and condition specific." (PMID 29789718, 2018).
osteosarcoma (2 papers, 2020 to 2023). A usually aggressive malignant bone-forming mesenchymal neoplasm, predominantly affecting adolescents and young adults. "However, a few studies have also shown that PDLIM7 exerts oncogenic functions, such as the downregulation of PDLIM7 expression in osteosarcoma (OS) tissues and the inhibition of cell proliferation and migration by PDLIM7 overexpression in OS cells." (PMID 37894409, 2023).
skin tumors (2 papers, 2011 to 2019). "Although little is currently known about potential roles that Pdlim7 may play in cancer tumorigenicity or metastasis, gene expression analysis of skin tumors identified Pdlim7 to be more highly expressed in metastatic compared with nonmetastatic tumors." (PMID 30692208, 2019).
Thrombosis (2 papers, 2013 to 2016). "Genetic inactivation of Pdlim7 in the murine model causes spontaneous systemic thrombosis, leading to early perinatal lethality." (PMID 27792740, 2016). "In the murine model, a deficiency in Pdlim7 causes spontaneous systemic venous and arterial thrombosis, resulting in significant lethality." (PMID 27792740, 2016).
bladder cancer (1 paper, 2025). "Subsequent box plot analysis further demonstrated significantly lower expression of six genes (LIMS2, IRAK3, STX2, IL11RA, KCNMB1, and PDLIM7) in bladder cancer cell lines, consistent with bioinformatics analysis." (PMID 40755754, 2025). "Although this study revealed an important regulatory role of PDLIM7 in bladder cancer, its specific molecular mechanisms and clinical translational potential require systematic validation through in vitro and in vivo functional experiments." (PMID 40755754, 2025). "Differential expression analysis revealed that, compared to the normal bladder cell line SV, the expression levels of LIMS2, IL11RA, KCNMB1, and PDLIM7 were significantly downregulated in all three bladder cancer cell lines (5637, T24, and HT1376)." (PMID 40755754, 2025). "This study is the first to show that PDLIM7 is significantly downregulated in bladder cancer tissues and that its expression is negatively correlated with disease risk." (PMID 40755754, 2025). "Finally, intersecting these key genes with risk-consistent genes yielded eight immune-related genes that were negatively associated with bladder cancer risk: LIMS2, TP53INP2, IRAK3, STX2, CYP27A1, IL11RA, KCNMB1, and PDLIM7." (PMID 40755754, 2025). "Through integrated multi-omics analysis and experimental validation, six genes, LIMS2, IRAK3, STX2, IL11RA, KCNMB1, and PDLIM7, were selected as potential immune-related biomarkers for bladder cancer, providing promising biomarkers and therapeutic targets for personalized treatment." (PMID 40755754, 2025). "This study revealed the key role of PDLIM7 (PDZ and LIM domain protein 7) as an immune-related gene in bladder cancer." (PMID 40755754, 2025). "In vitro qRT-PCR validation in bladder cancer cell lines showed downregulation of LIMS2, IRAK3, STX2, IL11RA, KCNMB1, and PDLIM7, consistent with bioinformatics findings, suggesting that these genes may serve as potential therapeutic targets." (PMID 40755754, 2025). "The consistent downregulation of these genes in bladder cancer tissues was further validated using independent public datasets, and qRT-PCR experiments confirmed the differential expression of the following six genes: LIMS2, IRAK3, STX2, IL11RA, KCNMB1, and PDLIM7." (PMID 40755754, 2025).
cardiomyopathy (1 paper, 2020). A disease of the heart muscle or myocardium proper. "Intragenic-DMGs at 0.8% CO2 vs. 0.4% and 0.1% included: PDLIM7, whose resulting protein regulates valve annulus size and hemostasis; TGFB1, which regulates postnatal cardiomyocyte differentiation; and ILK, which has been shown to exhibit protective effects against cardiomyopathy." (PMID 33193638, 2020).
inflammatory bowel disease (1 paper, 2025). A spectrum of small and large bowel inflammatory diseases of unknown etiology. "For 6 of these genes, a role in inflammatory bowel disease is supported by other criteria: GWAS associations with nearby SNPs (ANKRD55, LPP, PDLIM7), experimental perturbation (CCDC50, VCAM1), association with measured protein levels (IL6, VCAM1), or drug effects (IL6, VCAM1)." (PMID 40996888, 2025).
liver cancer (1 paper, 2023). An epithelial or non-epithelial malignant neoplasm that arises from the liver. "Together, we here identified several new α‐catenin interacting partners such as PDLIM7 and CEP55, which exclusively interact with α‐catenin in the cytoplasm of liver cancer cells." (PMID 37381005, 2023).
mitral valve prolapse (1 paper, 2025). A fairly common and often benign valvular heart disorder characterized by redundancy or hooding of mitral valve leaflets so that they prolapse into the left atrium, often causing mitral regurgitation. "In the presented case of familial mitral valve prolapse, whole exome sequencing was used to reveal a missense variant in the PDLIM7 gene." (PMID 40161031, 2025).
muscular disease (1 paper, 2024). Myopathy is a peripheral nervous system disease consisting of any abnormal condition or disease of the muscular tissues; commonly designates a disorder involving skeletal muscle. "TPM1 and PDLIM7 are two genes with important roles in muscle development and muscular diseases." (PMID 37705195, 2024).
Obesity (1 paper, 2024). Accumulation of substantial excess body fat. "Herein, we focused on purified preadipocytes and have elucidated the anti-obesity role of ANXA1, PDLIM7 and MYCBP2 in the suppression of adipogenesis, along with the underlying molecular mechanisms." (PMID 39174522, 2024).
serous ovarian cancer (1 paper, 2019). "In contrast to the small gene set (IGF2BP1, SRF, FOXK1 and PDLIM7), the enlarged gene set (35 genes plus IGF2BP1 and SRF) was significantly associated with poor OS probability in serous ovarian cancer, HCC as well as LUAD, as supported by HR values ranging from 1.52 to 2.15." (PMID 30371874, 2019).
tumor (421 papers, 1996 to 2026). "In THCA, PDLIM7 is aberrantly highly expressed in all subtypes and positively correlates with lymphatic metastasis and tumor malignancy." (PMID 37894409, 2023). "Subcutaneous tumor analysis revealed that overexpression of PDLIM7 significantly enhanced YAP1 staining abundance in the nucleus." (PMID 36823643, 2023). "In agreement with promoting tumor cell vitality, PDLIM7 was shown to stabilizes MDM2 by interfering with its autoubiquitination resulting in reduced responsiveness toward CDK4/6-inhibition by PD03329921 in cancer cells." (PMID 30371874, 2019). "This study elucidates the coordinated interplay between osmotic tension and membrane potential in cellular electromechanics, revealing a mechanistic framework where osmotic tension asymmetry orchestrates tumor cell migration through polarized PDLIM7-microfilament tension regulation." (PMID 41431193, 2025). "Among them, PDLIM7, as the related gene with the greatest difference, was found to have a significant statistical difference in its distribution between normal tissues and tumor cells." (PMID 40861819, 2025). "We found that the RNA expression levels of PDLIM3, PAM, PDLIM7, FSCN1 and LGALS3 were significantly upregulated in tumor samples, which provides ideas for further studies." (PMID 36177006, 2022). "At the post-transcriptional level, IGF2BP1 maintains the expression of multiple SRF target genes, including PDZ and LIM domain 7 (PDLIM7) and forkhead box K1 (FOXK1), which further enhances tumor cell growth and invasion." (PMID 34692544, 2021). "To validate the expression levels of the eight key genes (LIMS2, TP53INP2, IRAK3, STX2, CYP27A1, IL11RA, KCNMB1, and PDLIM7) in tumor and non-tumor samples, we analyzed their expression in TCGA and GSE7476 datasets." (PMID 40755754, 2025). "IGF2BP1 promotes SRF expression in a conservative m6A-dependent manner by impairing the decay of SRF mRNA guided by miRNA, thereby promoting the expression of genes such as PDLIM7 and FOXK1 that can promote tumor cell growth, ultimately promoting tumor cell growth and invasion." (PMID 39062595, 2024). "PDLIM7 and FOXK1 promote tumor cell growth and were reported to enhance cell invasion." (PMID 30371874, 2019).
cancer (217 papers, 2003 to 2025). A tumor composed of atypical neoplastic, often pleomorphic cells that invade other tissues. "Pearson’s correlation analysis was operated to uncover the correlation pair between differentially expressed cancer-associated PDLIM7 and let-7g gene, whose correlation coefficient was −0.217, and p < 0.05." (PMID 38132395, 2023). "Moreover, recent studies have identified PDLIM7 in cancer-associated fibroblasts binding to calponin 1 protein and inhibiting its degradation by E3 ubiquitin ligase NEDD4-1." (PMID 37894409, 2023). "Our current objective is to investigate the correlation between PDLIM7 and let-7 gene expression using a limited amount of cancer tissue samples." (PMID 38132395, 2023). "It has been shown that impairment of miRNA-directed decay of transcription factors, such as serum response factor (SRF), increases the expression of PDLIM7 in cancer." (PMID 38132395, 2023). "If the SRF/IGF2BP1-dependent enhancement of FOXK1 and PDLIM7 has prognostic value in cancer, it was evaluated by Kaplan–Meier analyses using KM plotter." (PMID 30371874, 2019). "This regulation was associated with a substantial recovery of spheroid growth upon SRF depletion suggesting that FOXK1 and PDLIM7 are part of a SRF/IGF2BP1-dependent ‘effector network’ in cancer cells." (PMID 30371874, 2019). "Both transcripts (FOXK1 and PDLIM7) were decreased upon the knockdown of IGF2BP1 suggesting a substantial conservation of SRF/IGF2BP1-dependent regulation of both factors in cancer cells." (PMID 30371874, 2019). "Two of these 35 mRNAs, PDLIM7 and FOXK1, showing a significant and positive association with both, IGF2BP1 and SRF expression in cancer, as indicated for HCC and EOC, were chosen for validating regulation by IGF2BP1 and SRF." (PMID 30371874, 2019). "PDLIM7 plays a significant role in cancer development and progression." (PMID 37894409, 2023). "The majority of these SRF/IGF2BP1-enhanced genes, including PDLIM7 and FOXK1, show conserved upregulation with SRF and IGF2BP1 synthesis in cancer." (PMID 30371874, 2019).
PDLIM7 also shares sentences with these, for which no sentence is quoted: nasopharyngeal carcinoma (292 papers); lymphoma (123); infection (121); Burkitt lymphoma (72); Hodgkins lymphoma (72); B cell lymphoma (49); latent infection (43); gastric cancer (39); T-cell lymphoma (26); diffuse large B-cell lymphoma (20); viral infection (18); lymphoproliferative disorders (15); non-Hodgkin lymphoma (12); squamous carcinoma (11); infectious mononucleosis (9); lupus (9); cervical carcinoma (8); NK/T-cell lymphoma (8); classical Hodgkin lymphoma (7); lymph node metastasis (7); AIDS (6); colitis (5); colorectal cancer (5); post-transplant lymphoproliferative disorder (5); chronic lymphocytic leukemia (4); colon carcinoma (4); Epstein-Barr virus infection (4); gastric tumors (4); hematological malignancies (4); lymphoepithelial carcinoma (4).
A further 124 diseases each share a sentence with PDLIM7 in 4 papers or fewer.